PIGBOS1 (PIGB opposite strand 1)
Description:
Plays a role in regulation of the unfolded protein response triggered by endoplasmic reticulum (ER) stress resulting from the presence of unfolded proteins in the ER lumen.
Synonyms: HP06981
Gene: Protein-coding gene on chromosome 15 (55,317,175 to 55,319,419, reverse strand). Ensembl gene ENSG00000225973.
Subcellular location: Mitochondrion outer membrane
Gene Ontology:
Molecular function: protein binding
Biological process: regulation of endoplasmic reticulum unfolded protein response
Cellular component: mitochondrial outer membrane; mitochondrion
Homologues: Orthologues: chimpanzee PIGBOS1 (98% identical), pig PIGBOS1 (74% identical), rabbit PIGBOS1 (70% identical), rat Pigbos1 (70% identical), mouse Pigbos1 (67% identical), tropical clawed frog PIGBOS1 (50% identical).
Diseases named in the same sentence as PIGBOS1 in open-access papers:
PIGBOS1 is named in the same sentence as 3 diseases in open-access papers, as found by Europe PMC text mining. Sharing a sentence is not in itself a finding about the gene and the disease. The quoted sentences say what the papers report.
cutaneous melanoma (1 paper, 2017). A primary melanoma arising from atypical melanocytes in the skin. "A linear combination of six lncRNAs (LINC01260, HCP5, PIGBOS1, RP11-247L20.4, CTA-292E10.6 and CTB-113P19.5) was constructed as an indicator for the clinical outcome of patients with cutaneous melanoma." (PMID 29100423, 2017).
melanoma (1 paper, 2022). A malignant, usually aggressive tumor composed of atypical, neoplastic melanocytes. "Studies have found that patients with melanoma can be divided into high-risk groups and low-risk groups with different survival times by a molecular signature of six lncRNAs, including LINC01260, HCP5, PIGBOS1, RP11-247L20.4, CTA-292E10.6, and CTB-113P19.5." (PMID 35016686, 2022).
bacterial infection (1 paper, 2023). "Although PIGBOS1 has not been studied in fish, the results of this study suggested that it may maintain cellular homeostasis in the yellow drum during the response to bacterial infection." (PMID 37175446, 2023).